CD47 (CD47 molecule)
Diseases named in the same sentence as CD47 in open-access papers (continued):
Sharing a sentence is not in itself a finding about the gene and the disease.
tumor (continued). "Another preclinical study demonstrated that the combination of CD47 mAb Hu5F9-G4 and trastuzumab in the treatment of Her2+ breast cancer cells significantly overcame the resistance to trastuzumab monotherapy and effectively inhibited tumor growth." (PMID 38787372, 2024). "In this study, we aimed to evaluate the correlation of CD47 expression with prognostic parameters (tumor type, tumor size, histological grade, pathological stage, capsular invasion, lymphovascular invasion, and the presence of metastasis) in cases of benign and malignant renal cell tumors." (PMID 39795582, 2024). "While CD47 × PD‐L1 BisAb and standard anti‐PD‐L1 therapy inhibited tumor growth compared to isotype control, the enhancement of myeloid populations within the spleen was only observed within the CD47 × PD‐L1 BisAb‐treated mice, whereas no changes were observed in the tumor." (PMID 39584189, 2024). "However, tumor cells upregulate the innate immune checkpoint CD47 under hypoxic conditions, counteracting NK cell-mediated cytotoxicity with the “do not eat me” signal." (PMID 38297372, 2024). "Furthermore, targeting CD47 is demonstrated to promote tumor vascular normalization through the heightened infiltration of CD4+ T cells." (PMID 38398223, 2024). "Furthermore, tumour cells employ ‘don’t eat me’ signals, such as signals mediated via the CD47-SIRPα axis or CD24-Siglec10 axis, that block antigen presentation by TAMs15." (PMID 39025845, 2024). "Their ability to modulate TAMs may contribute to their anti-tumour effects beyond their role in bone protection, in addition, antibody-drug conjugates (ADCs) targeting antigens such as CD47, CD163, and CSF1R are being investigated." (PMID 38794316, 2024). "Connection of CD47 and SIRPα could transmit inhibitory signals to prohibit macrophage phagocytosis, leading to immune evasion of tumor cells and ultimately promoting tumor development." (PMID 38317230, 2024). "Thus, our study reveals an important role of IFN-I in reprograming tumor cell metabolism for antitumor immunity during CD47-SIRPα blockade and highlights the importance of tumor cell OXPHOS in immunotherapy." (PMID 38982116, 2024). "Therefore, inhibiting the interaction of CD47/SIRPα can be an effective strategy for enhancing the phagocytic clearance of tumor cells from the body." (PMID 38983860, 2024). "Ever since the CD47-Signal-Regulatory Protein α (SIRPα) axis was identified as the initial checkpoint for tumor phagocytosis in the late 2000s, several other phagocytosis checkpoints responsible for enabling tumor cells to evade phagocytic elimination have come to light." (PMID 38881902, 2024). "Indeed, anti‐CD47 antibody treatments are effective at reducing tumor burden and have been recently found to affect CD8+ T cell function by enhancing dendritic cell (DC) and macrophage activation." (PMID 39584189, 2024). "Moreover, CXCL12 released by TECs and BoxA, a fragment of HMGB1, can engage the CXCR4-CD47 complex and trigger CD47 internalization to release a phagocytosis signal by the tumor cells and attract macrophages." (PMID 38726320, 2024). "Overall, these studies suggest that combining HDACis with anti-CD47 could modulate the CD47/SIRPα axis, enhance phagocytosis, and decrease tumor growth by enhancing the antitumor immune response." (PMID 38414061, 2024). "The reason for low immune cell infiltration in tumor tissues of CD47-MET fusion NSCLC is currently unknown." (PMID 38957460, 2024). "The ability of CD47-blocking agents to induce apoptosis of CD47-hyperexpressing cancer cells may allow the suppression of tumor growth in a tumor xenotransplant animal model." (PMID 38247566, 2024). "In addition to suppressing primary tumor progression and reducing metastasis, anti-CD47 treatment can synergize with immune checkpoint inhibitors to augment anti-neoplastic effects in some preclinical models." (PMID 39003350, 2024). "In GBM, tumor cells highly express CD47, an antiphagocytosis signal." (PMID 38226619, 2024).
tumor (continued). "Blocking the CD47/SIRPα pathway has been shown to activate macrophages and inhibit tumor growth." (PMID 38462636, 2024). "In addition, CD47 molecules on the surface of gETL NPs bound to the signal regulatory protein alpha receptor (SIRPα) on macrophages, preventing tumor cells from escaping the immune system, thus enhancing macrophage phagocytosis of tumor cells." (PMID 39802949, 2024). "The mAb of CD47 targets the CD47-SIRPα pathway, and converts TAMs into anti-tumor properties." (PMID 39169402, 2024). "However, CD47 blockade alone is insufficient to fully stimulate macrophage-mediated anti-tumor activity as it requires concurrent “eat me” signals." (PMID 38398223, 2024). "It controls CD47 and PD-L1 expression in diverse tumor cells, impacting immune checkpoint pathways; the overexpression of these molecules driven by Myc inhibits both innate and adaptive immune responses, thereby promoting tumor progression." (PMID 38534385, 2024). "Therefore, disrupting the CD47/SRIPa axis via monoclonal antibodies switches and re-educates TAMs from the tumor-promoting phenotype into the pro-inflammatory M1-like phenotype with enhanced phagocytotic behavior." (PMID 38672714, 2024). "Moreover, genetic deletion of the SIRPA ligand Cd47 on tumour cells also restricted tumour growth in Clec4fcreId3f/f mice and rescued CD8 T cell and NK cell recruitment to wild-type levels." (PMID 38326607, 2024). "Therefore, CSC plays a crucial role in finely modulating the immune microenvironment and inhibiting anti-tumor immune responses through various mechanisms, such as the expression of CD47, CD200, the CLOCK/BMAL1/OLFML3 pathway, and IL1R2." (PMID 39184916, 2024). "They observed that CD47 was highly expressed in this tumor cell line." (PMID 38832992, 2024). "Therefore, this integrated lipid metabolic pathway can enhance macrophage phagocytosis of CD47+tumor cells, providing a potential target for targeted TAM metabolic therapy." (PMID 38185636, 2024). "Furthermore, scRNA-seq analysis revealed that CD47 was substantially expressed in tumor cells, and we discovered that riskscore were positively linked with CD47, PDCD1, TIGIT, and LAG3." (PMID 37021054, 2023). "One significant limitation is that tumor cells can develop resistance to CD47-targeted therapy through various mechanisms, such as upregulating alternative phagocytic checkpoints or increasing expression of CD47 on the surface of tumor cells." (PMID 38188674, 2023). "Studies suggest that inhibiting the interaction between signal-regulatory protein α (SIRPα) and CD47 may enhance the ability of macrophages to eliminate tumor cells." (PMID 37666809, 2023). "Collectively, preclinical studies of CD47 blockade have demonstrated encouraging activity associated with enhanced phagocytic clearance of cancer cells and induction of anti-tumor immunity, stimulating the development of numerous agents for CD47-targeted therapy." (PMID 37958404, 2023). "Similarly, it was found that administration of anti-CD47 antibodies increased macrophage phagocytosis of both glioma cells and GSCs, with decreases in tumor growth and increased survival time in animal models." (PMID 37275361, 2023). "An immunodeficient mouse model that lacks mouse T, B and NK cells and that provides phagocytic tolerance (e.g., via SIRPANOD, human SIRPA transgene (SIRPATg), human SIRPA knock-in (SIRPAKI) or mouse CD47−/−) is necessary to prevent rejection of transplanted human immune and tumor cells." (PMID 37296949, 2023). "Consequently, cell surface calreticulin expression on tumor cells positively correlates with degree of anti-CD47 activity." (PMID 37468567, 2023). "Nevertheless, anti-CD47 medications exert their anti-tumor effects through distinct pathways." (PMID 37822610, 2023).
tumor (continued). "Notably, the CD47 antibody dramatically restored the phagocytosis of RAGA knockdown cells to the level of control cells, supporting the notion that the phagocytic inhibition of RAGA knockdown tumor cells is dependent on increased CD47 accumulation." (PMID 36823443, 2023). "Then the three as‐obtained nanovesicles were mixed to form HMNVs, which could not only block the CD47/SIRPα signaling pathway but also promote M2‐to‐M1 reprogramming within tumor tissues, eventually leading to a remarkable effect of tumor immunotherapy." (PMID 37749882, 2023). "Indeed, CD47-enriched EVs were demonstrated to escape phagocytosis and presented an increase in RNA accumulation into tumor cells." (PMID 37237479, 2023). "Thus, our development of a tumor selective, pH-dependent antibody reconciles therapeutic efficacy with safety to support anti-CD47 therapies against solid tumors." (PMID 36650558, 2023). "High CD47 expression was also positively correlated with advanced tumor grade and poor survival." (PMID 36413402, 2023). "Blockade of CD47/SIRPα, the “don’t eat me” axis, promotes phagocytosis of tumor cells." (PMID 37510993, 2023). "CD47 is an immunoglobulin which is overexpressed in many different tumor cells." (PMID 37927570, 2023). "Additionally, we will focus on the latest advancements in CD47-based immunotherapy for non-neoplastic diseases and propose several strategies to address the current challenges faced in CD47-based immunotherapy." (PMID 38125492, 2023). "We conjugated collagen-binding domain TKKTLRT to SIRPαFc fusion protein with a short chemical linker Sulfo-SMCC, which could block immune checkpoint CD47 and promote anti-tumor phagocytosis to suppress tumor growth." (PMID 37692860, 2023). "However, blocking CD47 can transform TAMs into antitumor state and enable more macrophages to recruit to the tumor." (PMID 37719086, 2023). "This could be a greater issue for solid cancers due to the inherent complexities of tumor stroma and vasculature that can impede antibody delivery, which might explain the lower efficacy of CD47 mAb in solid tumor patients." (PMID 37958404, 2023). "Notably, CD47 Y286F and CD47 K99/102R expression increased and decreased phagocytosis of the GFP‐expressing tumor cells by infiltrated tumor‐associated macrophages (TAMs), respectively, as detected by immunofluorescence staining of F4/80 a macrophage marker." (PMID 37541303, 2023). "CD47 (also called integrin-associated protein, IAP) is a cell surface transmembrane glycoprotein widely expressed on many cells of epithelial and mesenchymal origin and is highly expressed on tumor cells." (PMID 36882648, 2023). "In addition to these cancer cell-intrinsic effects, CD47–integrin interactions can influence tumor immunity by modifying the behavior of immune cells in the TME." (PMID 37958404, 2023). "Investigators have identified several tumor-phagocytosis-related checkpoints, including the CD47/signal regulatory protein α (SIRPα) axis, the PD-1/PD-L1 axis, the MHC-I/leukocyte immunoglobulin-like receptor subfamily B (LILRB1) axis, and the CD24/SIGLEC10 axis." (PMID 38033495, 2023). "Signal-regulatory protein α (SIRPα) expressed by myeloid cells is of particular interest for therapeutic strategies targeting the interaction between SIRPα and the “don’t eat me” ligand CD47 and as a marker to monitor macrophage infiltration into tumor lesions." (PMID 38164132, 2023). "Previous studies have reported that in oncological diseases, the interplay between CD47 overexpression in tumour cells and counter ligand signal regulatory protein-α (SIRPα) expression in macrophages initiates the “don’t eat me” signal, which inhibits the capacity of macrophage phagocytosis." (PMID 38037074, 2023). "Also, the expression of CD47 or CD24 molecules protecting against phagocytosis on tumor cell-derived EVs has been reported." (PMID 37476156, 2023).
tumor (continued). "In addition, they have targeting immunosuppressive mechanisms in the tumor microenvironment, such as anti-CD47, which targets the don’t eat me signal on tumor promoting macrophages." (PMID 39917366, 2023). "The preferential blockage of CD47 on tumor cells remains a significant challenge." (PMID 36959204, 2023). "Herein we describe a first-in-class and rationally designed bispecific antibody (BsAb), HX009, targeting PD1 and CD47 but with weakened CD47 binding, which selectively hones the BsAb for tumor microenvironment through PD1 interaction, potentially reducing toxicity." (PMID 37012357, 2023). "Several publications showed that knocking out CD47 on tumor cells could enhance macrophage phagocytosis, antigen presentation and T cell infiltration in different animal models." (PMID 36593962, 2023). "Expression of CD47 prevents cancer cells from being phagocytosed and thus promotes tumor growth." (PMID 37143666, 2023). "Therefore, strategies targeting the CD47/SIRPα axis to enable tumor cell killing through cellular phagocytosis have emerged as promising cancer immunotherapies." (PMID 37706196, 2023). "Here, we will review the role of macrophages in anti-tumor immunotherapy, involving the depletion, repolarization of TAMs, and the blockage of the CD47-SIRP pathway to improve phagocytosis with cancer therapy, to clarify the significance of macrophages in tumor therapy." (PMID 36903458, 2023). "Anti-CD47 can selectively target tumor cells since tumor cells express CD47 at high levels." (PMID 37345054, 2023). "Blocking the SIRPα/CD47 axis could not only activate adaptive anti-tumor immune responses by promoting antigen cross-presentation by APCs, but also could activate innate immune responses by enhancing the cancer cell clearance by macrophages and DCs." (PMID 37510993, 2023). "CD47 blocks the drive for T cell-mediated immune tumor eradication." (PMID 37854883, 2023). "Similarly, CAR T-cells that target CD-47, a macrophage immune checkpoint, have demonstrated significant anti-tumor immunity in the treatment of CD-47-positive pancreatic, ovarian, and melanoma tumors." (PMID 37020537, 2023). "In addition, using mIHC staining, PD-L1 and CD47 were demonstrated co-expression on several types of tumor cells." (PMID 36593962, 2023). "Importantly, the combination of low-dose anti-CD47 antibody with ACOD1-/- MSLN-iMACs had the most superior tumor suppression effect." (PMID 37723178, 2023). "To study the overcoming of resistance to therapeutic IgA therapy in cancer cells through CD47 blockade, we investigated the combination of IgA antibodies and disruption of the CD47/SIRPα axis, a well-studied myeloid checkpoint pathway, in the context of tumor cell killing by neutrophils." (PMID 37444515, 2023). "In addition, T-cell-mediated adaptive immune response acts crucially in anti-CD47 blockade-triggered tumor control." (PMID 37063284, 2023). "IHC staining results further confirmed the comparable CD47 expression in the 2 tumor models." (PMID 36939440, 2023). "CD47 is expressed in a variety of tumor cells, and mediates a “don’t eat me” signal after binding the immune checkpoint protein SIRP-α expressed on myeloid cells (monocytes, macrophages, and DCs), which contributes to the resistance of tumors to phagocyte-dependent clearance." (PMID 37064113, 2023). "Notably, the combined treatment of afatinib and the anti‐CD47 antibody resulted in an additive effect on tumor growth inhibition and mouse survival prolongation." (PMID 37541303, 2023). "In addition, tumor cells avoid being engulfed by innate immune cells by overexpressing CD47, a kind of “don't eat me” signal." (PMID 36999977, 2023). "When CD47 binds to SIRPα on macrophages, it can promote the clearance of tumor cells." (PMID 37208386, 2023).
tumor (continued). "Note that the expression of TIM3 and CD47 markers on NCH644 tumor cells also increased after culturing with dendrimers: NCH644 cells responded to the use of AE2G3 by increased TIM3 expression (p = 0.03), NCH644 cells responded predominantly to AE2G3 addition, as in the case of PD-L1." (PMID 36986829, 2023). "Additionally, CD47-targeted CAR T-cell therapy has demonstrated potent anti-tumor effects in preclinical models." (PMID 38188674, 2023). "The study suggests that a combination of blocking different inhibitory interactions, such as CD47/SIRPα and sialic acids/Siglec, may be necessary to optimize cancer immunotherapy, considering the ways in which tumor cells evade the immune system." (PMID 37444515, 2023). "Here, we investigate whether CTCs and/or circulating tumor cell clusters (CTM) from NSCLC patients express CD47 and TGF-β receptor (two immune escape molecules) and their prognostic implications." (PMID 37569332, 2023). "Our study showed triple combining therapy with FOLFOX, CD47 and PD-L1 is an effective treatment regimen in CT-26 mice tumor model and may consider as a potential to translate to the clinic." (PMID 36774400, 2023). "Several studies reported that PD‐L1 and CD47 also played a vital role in regulating immune‐unrelated biological processes in tumour cells, moreover, antagonising PD‐L1 or CD47 could inhibit the tumour cell proliferation and migration and induce apoptosis." (PMID 37974395, 2023). "Interestingly, we found that higher levels of Cd47 correlated with reduced phagocytosis of tumor cells by immune cells." (PMID 37095087, 2023). "Collectively, these data suggested that Abrine could promote the phagocytosis of tumor cells by macrophages and prevent the immune escape of tumor cells by inhibiting the expression of CD47." (PMID 37334368, 2023). "Consequently, preventing CD47/SIRPα cross-talk stimulates the innate and adaptive immune responses, resulting in tumor-cell apoptosis." (PMID 38033495, 2023). "Our models might therefore not recapitulate the antitumor effect of SE12C3 dependent on DCs—in particular, that mediated by the cGAS-STING pathway, which is activated by anti-CD47 in a syngeneic mouse tumor model." (PMID 38162643, 2023). "The efficacy of CD47 blockade has also been demonstrated in human tumor xenografts." (PMID 37958404, 2023). "Besides, the released RRX-001, as a CD47 inhibitor currently under clinical trials, downregulates CD47 proteins on tumor cell membrane." (PMID 37951973, 2023). "A microfluidics‐enabled nanovesicle using ultra‐pH‐sensitive polymer mannose‐poly(carboxybetaine methacrylate)‐poly(hydroxyethyl piperidine methacrylate) (Man‐PCB‐PHEP) is developed to deliver CD47/PD‐L1 antibodies (NCPA) for tumor‐acidity‐activated immunotherapy." (PMID 37132609, 2023). "Alternatively but also importantly, tumor cells of high CRT expressions in the plasma membrane may escape the macrophage clearance by overexpressing the “don’t-eat-me” CD47 checkpoint signaling molecule on tumor cell surfaces." (PMID 37951973, 2023). "CD24 and CD47 are both expressed abnormally on tumor cells and express in normal tissues." (PMID 37484024, 2023). "CD47 is a tumor antigen that can block phagocytosis of tumor cells by macrophages." (PMID 37746282, 2023). "In addition, as 5-fluorouracil (5-Fu)-based chemotherapy is the cornerstone in GCLM treatment, we administered a combination of anti-CD47 antibodies and 5-Fu, which acted synergistically to suppress the tumor." (PMID 36860925, 2023). "Moreover, the authors showed that treatment of tumor cells with berberine increased the efficiency of phagocytosis in the presence of an anti-CD47 antibody." (PMID 38275991, 2023). "Previously, our group reported a CBD-SIRPαFc conjugate as a novel tumor-targeting CD47 inhibitor." (PMID 37692860, 2023).